RN7SKP143 (RN7SK pseudogene 143)
Gene: Miscellaneous RNA gene on chromosome 10 (90,163,651 to 90,163,960, reverse strand). Ensembl gene ENSG00000222451.
Homologues: Orthologues: chimpanzee 7SK (99% identical). Paralogues in human: RN7SKP203 (72% identical), RN7SKP250 (70% identical), RN7SKP9 (70% identical), 7SK (70% identical), RN7SKP131 (70% identical), RN7SKP63 (70% identical), RN7SKP151 (69% identical), RN7SKP221 (69% identical), RN7SKP79 (69% identical), RN7SKP217 (69% identical), RN7SKP78 (69% identical), RN7SKP176 (69% identical), and 284 more.